TPGS1 (tubulin polyglutamylase complex subunit 1)
Description:
Subunit of the tubulin polyglutamylase complex (TPGC). The complex mediates cilia and flagella polyglutamylation which is essential for their biogenesis and motility (Probable). May act in the targeting of the tubulin polyglutamylase complex. Required for the development of the spermatid flagellum (By similarity).
Synonyms: PGs1; C19orf20; GTRGEO22
Tractability: PROTAC: ubiquitination databases record sites on it; its protein half-life has been measured.
Gene: Protein-coding gene on chromosome 19 (507,497 to 519,654, forward strand). Ensembl gene ENSG00000141933.
Subcellular location: Cytoplasm, cytoskeleton, cilium axoneme; Cytoplasm, cytoskeleton, flagellum axoneme; Cytoplasm, cytoskeleton, cilium basal body; Cytoplasm, cytoskeleton, flagellum basal body; Cell projection, axon; Cell projection, dendrite; Cytoplasm, cytoskeleton, microtubule organizing center, centrosome; Cytoplasm, cytoskeleton, microtubule organizing center, centrosome, centriolar satellite
Pathways (Reactome):
Metabolism of proteins: Carboxyterminal post-translational modifications of tubulin
Gene Ontology:
Molecular function: protein-macromolecule adaptor activity; microtubule binding; tubulin-glutamic acid ligase activity
Biological process: microtubule cytoskeleton organization; sperm axoneme assembly
Cellular component: centrosome; microtubule; catalytic complex; microtubule organizing center; axon; axoneme; centriolar satellite; dendrite
Genetic constraint (gnomAD): Loss-of-function variants: 21 observed, 8 expected, observed/expected ratio (o/e) 2.63. That is too few expected variants to judge how well the gene tolerates losing a copy. Missense variants: 500 observed, 283.78 expected, observed/expected ratio (o/e) 1.76, 90% interval 1.64 to 1.9. Synonymous variants: 247 observed, 147.98 expected, observed/expected ratio (o/e) 1.67, 90% interval 1.5 to 1.85.
Homologues: Orthologues: chimpanzee TPGS1 (99% identical), macaque TPGS1 (98% identical), dog TPGS1 (88% identical), pig TPGS1 (87% identical), mouse Tpgs1 (86% identical), rat Tpgs1 (86% identical), guinea pig TPGS1 (86% identical), rabbit TPGS1 (81% identical), zebrafish tpgs1 (35% identical).